FBLN5 (fibulin 5)
Diseases named in the same sentence as FBLN5 in open-access papers (continued):
Sharing a sentence is not in itself a finding about the gene and the disease.
lung carcinoma (continued). "FBLN5 may slow down the metastasis and invasion of lung cancer by inhibiting MMP-7 expression and promoting tumor metastasis through BM degradation." (PMID 37214471, 2023). "FBLN5 overexpression in H460 lung cancer cells also prevents metastasis in mice." (PMID 34976811, 2021). "Fibulin-3 and Fibulin-5 inhibit the invasion and metastasis of lung cancer (LC) cells by downregulating the expression of matrix metalloproteinase 7 (MMP-7), which promotes metastasis through degradation of the basement membrane that acts as barrier to the adjacent tissues." (PMID 30305430, 2018). "Therefore, the inhibitory effect of fibulin-5 on the Wnt pathway in lung cancer is mediated by the integrin-binding RGD motif." (PMID 25909283, 2015). "The functional role of fibulin-5 in suppression of lung cancer was investigated." (PMID 25909283, 2015). "Suppression of lung cancer metastasis by fibulin-5 may be mediated in part through c-Myc, which can promote lung cancer metastasis in mice." (PMID 25909283, 2015). "In addition to fibulin-5 silencing, several other aberrations in lung cancer can lead to activation of the Wnt pathway, such as overexpression of Wnt ligands, downregulation of Wnt antagonists such as dickkopf 3, and loss of fibulin-3 expression." (PMID 25909283, 2015). "Our results suggest that fibulin-5 silencing contributes to c-Myc overexpression in lung cancer." (PMID 25909283, 2015). "Fibulin-5 is known to be epigenetically silenced in lung cancer by promoter hypermethylation." (PMID 25909283, 2015). "We determined whether the effects of fibulin-5 on lung cancer invasion and MMP-7 expression are mediated by Wnt/β-catenin signaling, which is known to regulate MMP-7 expression in colorectal cancer cells." (PMID 25909283, 2015). "Since both MMP-7 and c-Myc are downstream effectors of the Wnt/β-catenin pathway, we hypothesized that the function of fibulin-5 in lung cancer is mediated through Wnt/β-catenin signaling." (PMID 25909283, 2015). "We further examined whether and how fibulin-5 regulates the Wnt/β-catenin pathway to suppress lung cancer invasion." (PMID 25909283, 2015). "FBLN5 is often silenced by promoter hypermethylation in NSCLC, which is the main reason why it is often downregulated in more than 50% of lung cancers." (PMID 37214471, 2023). "The effect of fibulin-5 is likely to be mediated by its binding to cell-surface integrins, as it requires the RGD motif that binds to αvβ3 in lung cancer cells." (PMID 25909283, 2015). "Together, these results indicate that fibulin-5 suppresses MMP-7 expression and lung cancer invasion through ERK inhibition and GSK3β activation, which in turn prevents β-catenin accumulation and nuclear translocation." (PMID 25909283, 2015). "Nonetheless, fibulin-5 expression did not induce substantial apoptosis in lung cancer cells (data not shown)." (PMID 25909283, 2015). "Our results suggest that fibulin-5 antagonizes Wnt signaling by inhibiting ERK and indirectly activating GSK3β to restrain β-catenin in the cytoplasm, which prevents MMP-7 and c-Myc expression and lung cancer cell invasion and proliferation." (PMID 25909283, 2015). "However, it is unclear how fibulin-5 inhibits MMP-7 expression and lung cancer cell invasion." (PMID 25909283, 2015).
ovarian carcinoma (8 papers, 2016 to 2025). A malignant neoplasm originating from the surface ovarian epithelium. "It was reported that FBLN5 modulates the inflammatory microenvironment, including macrophages in the dermis, and that tumor-associated macrophages degrade FBLN5 in epithelial ovarian cancer." (PMID 40943182, 2025). "The results indicate that downregulation of FBLN5 in ovarian cancer was accompanied by dramatic induction of MMP-9 and loss of its inhibitor, TIMP2." (PMID 29581841, 2018). "In epithelial ovarian cancer, FBLN5 is degraded by proteases prevalent in the tumor microenvironment macrophages, with the degraded form facilitating ovarian cancer cell adhesion and local metastasis." (PMID 40943182, 2025). "FBLN5 overexpression reduces tumor angiogenesis, suppresses lung adenocarcinoma and ovarian cancer progression, and has anti-tumor function." (PMID 36306007, 2022). "FBLN5 suppresses matrix metalloprotease 9, angiogenesis and epithelial cell motility in ovarian cancer, and blocks reactive oxygen species (ROS) in pancreatic cancer." (PMID 34874125, 2022). "We suggest that ovarian cancer cells stimulate MMP-7 production from tumor macrophages that readily degrade fibulin-5 thereby facilitating tumor progression and invasion." (PMID 29581841, 2018). "Given its role in cell adhesion and metastasis in other cancers, we sought to understand the role of FBLN5 in EOCs using cell adhesion assays and three ovarian cancer cell lines developed at our institution." (PMID 29581841, 2018). "Proteolysis of FBLN5 serves as a mechanism to promote cell adhesion and local metastasis of ovarian cancer cells." (PMID 29581841, 2018). "Degradation of FBLN5 would thereby increase MMP-9 protease activity or facilitate ovarian cancer cell adhesion to matrix substrates." (PMID 29581841, 2018). "Over expression of FBLN5 in ovarian cancer line SKOV3 inhibited migration and invasion in wound-healing and invasion assays." (PMID 27941907, 2016). "FBLN5 is a tumor suppressor that can inhibit the migration and invasion of ovarian cancer cells." (PMID 34475958, 2021). "Moreover, in epithelial ovarian cancer (EOC) and human endometrial cancer, its expression is down-regulated, which signifies that fibulin-5 acts as a tumor suppresser for ovarian cancer." (PMID 34063320, 2021). "Taken together, the data suggest that FBLN5 is degraded in epithelial ovarian cancer possibly by tumor macrophages that support tumor growth by degrading the matricellular protein thereby leading to increased angiogenesis and upregulation of MMP-9 to further support the invasive phenotype of EOC." (PMID 29581841, 2018). "Promotion of a stable ECM with intact FBLN5 in the tumor matrix may serve as a novel therapeutic adjunct to prevent spread of ovarian cancer." (PMID 29581841, 2018). "Here, we investigated the regulation and function of FBLN5 in epithelial ovarian cancer (EOC)." (PMID 29581841, 2018). "Therefore, FBLN5 acts as a tumor suppressor in ovarian cancer." (PMID 27941907, 2016). "Having established increased immunoreactive degradative products of FBLN5 in EOC, next we used immunohistochemistry to localize the protein in these human epithelial ovarian cancers." (PMID 29581841, 2018). "FBLN5 significantly inhibited EOC cell adhesion to both laminin and collagen I. One physiologic function of FBLN5 is likely to decrease the ability of malignant epithelial ovarian cancer cells to adhere to ECM proteins laminin and type I collagen." (PMID 29581841, 2018).
age-related macular degeneration (7 papers, 2012 to 2024). Age-related loss of vision in the central portion of the retina (macula), secondary to retinal degeneration. "AOC3 (amine oxidase copper containing 3) was implicated by causal genes ELN and FBLN5 in age related macular degeneration which typically develops post-middle age, but it has previously been associated with Autosomal Dominant Cutis Laxa." (PMID 39480826, 2024). "In 1.7% of age-related macular degeneration (AMD) patients, missense mutations in fibulin-5 were found, and structural analysis of CL and AMD mutations revealed that the mutations in fibulin-5 altered the structure, which may contribute to AMD and CL." (PMID 35456902, 2022). "As a result of the interaction with MPPs, the proteolytic activity of HtrA1 against Fibulin-5, a specific HtrA1 substrate in age-related macular degeneration (AMD), was increased." (PMID 25506911, 2014).
emphysema (7 papers, 2014 to 2023). "FBLN5 mutation or downregulation causes skin relaxation, vascular sclerosis, emphysema, and other senile diseases." (PMID 37644092, 2023). "Patients with fibulin-5 (DANCE) mutations develop ARCL1A, characterised by loose skin, emphysema and arterial tortuosity." (PMID 30016650, 2019). "Fibulin-5 is an important contributor to elastic fiber formation, as indicated by the appearance of abnormal elastic lamina formation in the aorta, and the development of pulmonary emphysema, loose skin, and tortuous vessels in Fbln5-/- mice." (PMID 27304216, 2016).
gastric cancer (6 papers, 2016 to 2025). A primary or metastatic malignant neoplasm involving the stomach. "In gastric cancer studies, high fibulin-5 expression correlates with more aggressive clinicopathologic features, such as poor differentiation, lymph node metastasis, advanced TNM stage and worse clinical outcome." (PMID 40369121, 2025). "Furthermore, the presence of fibulin-5 in blood samples from patients with gastric cancer and its correlation with primary tumor tissue, suggests FBLN5 as a plasma biomarker for both treatment response and prognosis." (PMID 40369121, 2025). "Similarly, IHC staining revealed a higher average H score for FBLN5 in tumors from patients with advanced gastric cancer (AGC) (n = 7) compared with normal gastric tissues from non-cancer subjects (n = 3; P = 0.001)." (PMID 40369121, 2025). "The purpose of this study was to investigate the effect of high expression of FBLN5 on the prognosis of gastric cancer (GC) patients." (PMID 36672502, 2023). "In conclusion, our study revealed the role of ANXA1, NNMT, Fibulin-5 and UQCRC1 in gastric cancer progression." (PMID 27941907, 2016).
hepatocellular carcinoma (6 papers, 2018 to 2023). A malignant tumor that arises from hepatocytes. "The analysis results showed that FBLN5 levels were also indicative for the prognosis of hepatocellular carcinoma, and the application prospects of FBLN5 in hepatocellular carcinoma are expected to be further explored in clinical practice." (PMID 36672502, 2023). "This idea is supported by the findings that reduced expression of FBLN5 correlates with poor prognostic features in hepatocellular carcinoma, and FBLN5 negatively regulates MMP-7 in these cells." (PMID 29581841, 2018). "FBLN5 inhibited the movement of hepatocellular carcinoma through an integrin-dependent mechanism." (PMID 36672502, 2023). "Additionally, FBLN5 is a potential indicator of therapeutic efficacy in patients with hepatocellular carcinoma." (PMID 37061682, 2023). "Finally, we explored the roles of FBLN5 in evaluating other cancers through bioinformatics and our results showed that FBLN5 had good application prospects for assessment of the prognosis of patients with hepatocellular carcinoma." (PMID 36672502, 2023). "High expression of FBLN5 was significantly correlated with better OS and DFS in hepatocellular carcinoma patients." (PMID 34550275, 2021). "Several hepatocellular carcinoma (HCC) cell lines display a low expression of fibulin-5, and suggest that fibulin-5 may inhibit HCC invasion and metastasis by suppressing the MMP-7 expression." (PMID 34063320, 2021).
liver fibrosis (6 papers, 2015 to 2026). "Given above, our results expand on existing knowledge by identifying plasma FBLN5 as a potential biomarker for liver fibrosis." (PMID 41362817, 2026). "We aimed to clarify the utility of plasma fibulin-5 (FBLN5), a component of elastic fibers, in assessing liver fibrosis in patients with chronic hepatitis." (PMID 41362817, 2026). "When comparing plasma FBLN5 with collagen type IV, a well-known marker of liver fibrosis, FBLN5 showed an additive value for predicting advanced fibrosis or cirrhosis." (PMID 41362817, 2026). "In IHC of FBLN5 in 72 liver biopsy samples, the FBLN5-positive area significantly increased in correlation with the liver fibrosis stage." (PMID 41362817, 2026). "Proteomics analysis revealed that liver FBLN5 expression correlates with the degree of liver fibrosis." (PMID 41362817, 2026). "Lastly, we evaluated the utility of plasma FBLN5 for predicting liver fibrosis in patients with hepatitis C." (PMID 41362817, 2026). "Among those were homologs of known human liver fibrosis markers such as Apolipoprotein A-IV or Fibulin-5." (PMID 34920711, 2021). "Although FBLN5 may represent a potential therapeutic target for liver fibrosis, safety concerns arise from data showing that FBLN5 knockout mice develop lethal vascular complications during embryogenesis." (PMID 41362817, 2026). "Therefore, we conclude that plasma FBLN5 has the potential to identify liver fibrosis, particularly in relation to activated HSCs." (PMID 41362817, 2026). "Therefore, we aimed to evaluate the usefulness of peripheral FBLN5 as a potential biomarker for liver fibrosis." (PMID 41362817, 2026). "Finally, we found that peripheral plasma FBLN5 levels were predictive of advanced fibrosis, suggesting its potential utility as a noninvasive marker for liver fibrosis." (PMID 41362817, 2026). "In addition, the utility of FBLN5 should be investigated in liver fibrosis with etiologies other than hepatitis C. While we conducted snRNA-seq analysis to confirm upregulation of FBLN5 in steatotic liver disease, more comprehensive studies are needed." (PMID 41362817, 2026). "Finally, we investigated whether plasma FBLN5, a noninvasive marker, could predict the degree of liver fibrosis in patients with chronic hepatitis C." (PMID 41362817, 2026). "Our findings are consistent with these studies, showing that HSCs activated by TGF-β1 produced FBLN5, highlighting the role of TGF-β as a strong activator of human HSCs and a main contributor in liver fibrosis progression." (PMID 41362817, 2026). "In liver biopsy samples obtained from patients with chronic hepatitis C, FBLN5 was coexpressed with elastic fiber and αSMA, an activated HSC marker, and its expression correlated significantly with the stage of liver fibrosis." (PMID 41362817, 2026). "EFEMP1 and FBLN5 are ECM proteins and highly express in portal fibroblasts, they have been proved to play a role in progressive liver fibrosis." (PMID 33971821, 2021). "Measurements of other new potential biomarkers for staging liver fibrosis such as fibulin-5, MMP-2 or TIMP-1 further have the potential to improve the accuracy of non-invasive estimates of liver fibrosis." (PMID 26460565, 2015). "Since the formation of hepatic fibrosis is a complex process of multi-factor and multi-cell involvement, our findings also point to the possible involvement of VACN, COL1A1, COL1A2, LUM, and FBLN5 in the generation of fibrotic response from NAFL to NASH." (PMID 36329886, 2022). "Another limitation is that we could not compare the value of plasma FBLN5 to that of any noninvasive imaging elastography, which is becoming a standard technique for estimating the grade of liver fibrosis." (PMID 41362817, 2026).
atherosclerosis (5 papers, 2022 to 2024). A disease characterized by the build-up of fatty material and calcium deposition in the arterial wall resulting in partial or complete occlusion of the arterial lumen. "Furthermore, FBLN5 has been implicated in the regulation of vascular smooth muscle cell proliferation and migration, which are processes that contribute to the development of atherosclerosis and thrombosis." (PMID 38649864, 2024). "Both Fbln5 and Vcam1 were upregulated in genuine endothelial precursor cells of mice with advanced atherosclerosis administered with a Western diet, implying that it induced more leukocytes that migrated to sites of inflammation." (PMID 36910156, 2023).
cervical cancer (5 papers, 2017 to 2023). A primary or metastatic malignant neoplasm involving the cervix. "Researchers also reported that Nogo-b is able to promote EMT in HeLa cervical cancer cells via Fibulin-5." (PMID 29050340, 2017). "However, its isoform RTN4B promotes the epithelial-mesenchymal transition of HeLa cervical cancer cells via Fibulin-5, an extracellular matrix protein." (PMID 35428758, 2022). "FBLN5 expression was decreased in lung adenocarcinoma, cervical cancer, and prostate cancer." (PMID 36306007, 2022). "The results showed that PLCB4, FBLN5, TSPAN8, CST6, and SERPINB7 were highly expressed in cervical cancer tissues (p<0.05)." (PMID 36408178, 2022).
pancreatic cancer (5 papers, 2020 to 2023). "It is worth mentioning that FBLN5 can block ROS production and oxidative damage elicited by fibronectin-β1 integrin signaling in pancreatic cancer via competing with fibronectin for β1 integrin binding." (PMID 37644092, 2023). "A study has revealed that hypoxia induces Fbln5 in a TGF-βRI/ALK5-dependent and Smad4-independent manner, and hypoxia and TGF-β increase the expression of Fbln5 in pancreatic cancer." (PMID 35625561, 2022). "Fibulin-5 (Fbln5) is a matricellular protein that reduces microenvironmental reactive oxygen species (ROS) and protects pancreatic tumor cells." (PMID 35625561, 2022). "In addition, hypoxia and TGF-β synergistically induced high FBLN5 expression levels in pancreatic cancer." (PMID 36672502, 2023). "FBLN5 also enabled the promotion of tumor metastasis in pancreatic cancer, cervical cancer, and GC." (PMID 36672502, 2023). "FBLN2, FBLN3, and FBLN5 have been shown to regulate Notch, Insulin Growth Factor receptor (IGF1R), EGFR signaling pathways, respectively, in glioma, lung, and pancreatic cancers." (PMID 32719793, 2020).
aortic aneurysm (4 papers, 2017 to 2022). A ruptured aneurysm located in the wall of the proximal portion of the descending aorta proceeding from the arch of the aorta. "By contrast, reduced SOX9 levels associated with fibulin-5 downregulation have been found in human aortic aneurysms, highlighting the different role of this factor depending on the pathology." (PMID 36499730, 2022). "Fbln5−/− mice show reduced contractility in the thoracic aorta and develop hypertension but do not give rise to aortic aneurysms or aortic dissection." (PMID 32801116, 2020).
colorectal cancer (4 papers, 2015 to 2021). A primary or metastatic malignant neoplasm that affects the colon or rectum. "Fibulin-5 is expressed lowly in colorectal cancer and correlated with clinicopathologic characteristics." (PMID 34475958, 2021). "Given its role in promoting apoptosis through TRPV1 downregulation and consequent ROS/MAPK and Akt signaling, fibulin-5 is a potential novel target in the treatment of colorectal cancer." (PMID 32545311, 2020). "Moreover, another ECM protein, fibulin-5, was reported to induce apoptosis in colorectal cancer cells by downregulating TRPV1 expression." (PMID 34131404, 2021). "Moreover, fibulin-5 is a multifunctional extracellular matrix protein with lower expression in colorectal cancer tissues than in peritumoral areas." (PMID 32545311, 2020). "Fibulin-5 expression substantially decreased the level of nuclear β-catenin in A549 and H1299 cells, and in SW480 colorectal cancer cells, which express abundant nuclear β-catenin." (PMID 25909283, 2015).